NKG7 (natural killer cell granule protein 7)
Description:
Regulates cytotoxic granule exocytosis in effector lymphocytes, thus acting as a critical mediator of inflammation in a broad range of infectious and non-infectious diseases (By similarity). Essential for cytotoxic degranulation of natural killer (NK) cells and CD8(+) T-cells and for the activation of CD4(+) T-cells following infection (By similarity). Plays a critical role in CD8(+) T-cell and NK cell-mediated cytolysis of target cells and contributes to the cytolytic activity via the perforin/granzyme pathway by enhancing exocytosis of LAMP1-carrying lytic granules (By similarity). Contributes to NK cell-mediated control of cancer metastasis (By similarity).
Synonyms: GMP-17; GIG1; p15-TIA-1
Tractability: Antibody: UniProt places it where antibodies can reach, with high confidence; its Gene Ontology location is reachable by antibodies, with high confidence; UniProt predicts a signal peptide or a membrane-spanning region.
Gene: Protein-coding gene on chromosome 19 (51,371,606 to 51,372,704, reverse strand). Ensembl gene ENSG00000105374.
Subcellular location: Cell membrane; Cytolytic granule membrane
Subcellular location (Human Protein Atlas): Vesicles
Gene Ontology:
Molecular function: protein binding
Biological process: defense response to protozoan; CD4-positive, alpha-beta T cell activation; granzyme-mediated programmed cell death signaling pathway; natural killer cell degranulation; natural killer cell mediated cytotoxicity; natural killer cell mediated cytotoxicity directed against tumor cell target; positive regulation of inflammatory response
Cellular component: cytolytic granule membrane; plasma membrane; cytolytic granule; membrane
Genetic constraint (gnomAD): Loss-of-function variants: 8 observed, 15.67 expected, observed/expected ratio (o/e) 0.51, 90% interval 0.3 to 0.92. The upper end of that interval is the gene's LOEUF score, 0.92, which puts it in group 3 of 6, group 1 being the genes least tolerant of losing a copy. Missense variants: 215 observed, 221.39 expected, observed/expected ratio (o/e) 0.97, 90% interval 0.87 to 1.09. Synonymous variants: 95 observed, 93.66 expected, observed/expected ratio (o/e) 1.01, 90% interval 0.86 to 1.2.
Homologues: Orthologues: chimpanzee NKG7 (96% identical), macaque NKG7 (87% identical), rat Nkg7 (72% identical), guinea pig NKG7 (70% identical), mouse Nkg7 (70% identical), pig NKG7 (70% identical), rabbit NKG7 (65% identical), dog NKG7 (58% identical). Paralogues in human: LIM2 (23% identical), GSG1L (22% identical), TMEM202 (20% identical), CLDND2 (18% identical), GSG1 (18% identical), GSG1L2 (17% identical), PMP22 (16% identical), EMP2 (16% identical), EMP1 (15% identical), EMP3 (14% identical).
Diseases named in the same sentence as NKG7 in open-access papers:
NKG7 is named in the same sentence as 65 diseases in open-access papers, as found by Europe PMC text mining. Sharing a sentence is not in itself a finding about the gene and the disease. The quoted sentences say what the papers report.
melanoma (9 papers, 2021 to 2024). A malignant, usually aggressive tumor composed of atypical, neoplastic melanocytes. "Recently, NKG7 expression in TILs has been associated with cytotoxicity in melanoma and was found to be upregulated in tumor antigen–specific CD8+ TILs." (PMID 39436696, 2024). "The expresson level of CD8+ T cells markers including CD8A, GZMB, NKG7, etc., was all shown to be higher in low risk melanoma patients." (PMID 34040608, 2021). "Moreover, we analyzed the expression level of gene CD3E, CD4, CD8A, GZMB, NKG7, TCF7 and TRBC2, the well-known markers for CD8+ T cells, and they were all shown to have significantly higher expression level in melanoma patients with low risk." (PMID 34040608, 2021). "A spate of recent studies have used diverse in vivo models to demonstrate a functional role for NKG7 in CD4+ T cells (visceral leishmaniasis), CD8+ T cells (malaria), NK cells (melanoma) and in CD8+ T cell driven anti-tumor immunity." (PMID 35874669, 2022). "As the aim of this work was to understand how melanoma TME affects the infiltration of CD8+ T cells, we excluded CD8+ T cell specific markers (CD8A, CD8B, GZMK and NKG7), as well as genes expressed in most CD8+ T cells (more than 50%) but in less than 10% of the remaining cells in the melanoma TME." (PMID 34040608, 2021).
COVID-19 (6 papers, 2020 to 2024). A disease caused by infection with severe acute respiratory syndrome coronavirus 2. "Specifically, compared to healthy controls, genes marking effector and cytotoxic CD8 T cell profiles (GZMB, NKG7, GZMH, PRF1, and CCL5) were upregulated in severe dengue and downregulated in severe COVID-19." (PMID 38294906, 2024). "We also found the specific downregulation of NKG7 and NEAT1 in innate-like T cells and NKs in COVID-19 patients." (PMID 36992700, 2023). "We found that NKG7, IL32, GZMA, PRF1, CST7, GZMH, and CCL5 were among the top DEG downregulated in CD3+ upon nasal Foralumab treatment of COVID-19 subjects." (PMID 36881624, 2023). "Performing this analysis for the COVID-19 patients demonstrated clear B- and T-cell clusters, defined by expression of TCF7, LEF1 (clusters 0 and 1), CD74, CD79A (clusters 2 and 3), IL7R (cluster 4) and CCL5, NKG7, GNLY (cluster 6)." (PMID 33884369, 2021). "Since NKG7 is important for cytotoxic degranulation and downstream inflammation and NEAT1 is an activator of the NLRP3 inflammasome, their downregulation may indicate an induced shift away from an inflammatory state in COVID-19 patients." (PMID 36992700, 2023). "We found that NKG7 was downregulated in CD8+ TEMRAs, CD8+ EM, non-VD2 gamma deltas, and gamma delta T cells when compared to baseline (day -2) in COVID-19-treated subjects but not untreated controls." (PMID 36881624, 2023).
Sepsis (5 papers, 2021 to 2025). Sepsis is defined as life-threatening organ dysfunction caused by a dysregulated host response to infection. "sc-RNA seq and assignment into two types of NK cells confirmed that heatstroke and sepsis were associated with lower number of NK cells than that in the other two groups, rather than affecting the relative abundance of CD56bri NK cells (NKG7+XCL1+) and CD56dim NK cells (NKG7+FGFBP2+)." (PMID 40084252, 2025). "Five genes (NKG7, SPTA1, FGL2, RGS2, and IFI27) have been proved to be potential biomarkers for sepsis-induced ARDS and exert crucial roles in the occurrence and development of sepsis." (PMID 36299685, 2022). "In summary, our study identified five key genes including NKG7, SPTA1, FGL2, RGS2, and IFI27, which were closely related to the sepsis-induced ARDS development." (PMID 34393665, 2021). "Furthermore, the widespread downregulation of specific cytotoxic and cytolytic genes, including GNLY, GZMH and NKG7, across CD8+ T cells, NK cells, CD56+ T cells, MAIT cells and γδ T cells reported here was found to negatively impact survival outcomes in sepsis." (PMID 41208955, 2025). "Moreover, five genes including NKG7, SPTA1, FGL2, RGS2, and IFI27 exhibited notable difference between the sepsis-induced ARDS group and the control group with sepsis alone in two datasets, suggesting that these five genes might be key genes that led to sepsis patients complicated with ARDS." (PMID 34393665, 2021). "Furthermore, five genes including NKG7, SPTA1, FGL2, RGS2 and IFI27 exhibited significant differences between the sepsis-induced ARDS samples and the samples with sepsis alone in two datasets, suggesting that these five genes might be key genes that led to sepsis patients complicated with ARDS." (PMID 34393665, 2021).
autoimmune disease (3 papers, 2021 to 2025). A disorder resulting from loss of function or tissue destruction of an organ or multiple organs, arising from humoral or cellular immune responses of the individual to their own tissue constituents. "Previous studies found that NKG7 was associated with cell cytotoxicity, particularly in the setting of inflammation and autoimmune diseases, as well as in antitumor immunotherapy." (PMID 40837024, 2025). "The identification of NKG7 as a regulator of cytotoxic lymphocyte function and inflammatory responses suggests that targeting this molecule may be a therapeutic approach to treat diverse conditions including infection, autoimmune diseases and cancer." (PMID 35874669, 2022). "Recent studies have reported that NKG7 is a regulator of granule exocytosis of CD8+ T cells in a variety of diseases, such as inflammatory and autoimmune disorders and cancer." (PMID 40837024, 2025).
ankylosing spondylitis (2 papers, 2021 to 2025). An autoimmune chronic inflammatory disorder characterized by inflammation in the vertebral joints of the spine and sacroiliac joints. "However, NKG7 expression was decreased in patients with ankylosing spondylitis." (PMID 40837024, 2025).
atherosclerosis (2 papers, 2023). A disease characterized by the build-up of fatty material and calcium deposition in the arterial wall resulting in partial or complete occlusion of the arterial lumen. "In both PSA and atherosclerosis CD8+ C3 T cells, expression profiles displayed a similar phenotype with high expression of T cell effector genes—for example, CCL5, GZMH, GZMA, GZMK and NKG7." (PMID 38665903, 2023).
liver cancer (2 papers, 2024 to 2025). An epithelial or non-epithelial malignant neoplasm that arises from the liver. "Another scRNA-seq-based study found CD4+ CTLs coexpressing Gzmb and Nkg7 in bladder and liver cancers." (PMID 38515134, 2024). "Another scRNA-seq-based study found the presence of CD4+ CTLs coexpressing Gzmb and Nkg7 in bladder and liver cancers." (PMID 38515134, 2024).
lymphoma (2 papers, 2022 to 2025). A malignant (clonal) proliferation of B- lymphocytes or T- lymphocytes which involves the lymph nodes, bone marrow and/or extranodal sites. "Here, we show that lymphoma samples contain cytotoxic CD4+ T cells, which were predominantly NKG7/TIA-1+GZMK+ TFH-like in FL and TIA-1+GZMK+ and/or GZMB+ within the CXCR5+PD-1+ and CXCR5–PD-1+ subpopulations of DLBCL." (PMID 41030456, 2025). "There were a number of genes related to apoptosis including Bcl2 (B-cell CLL/lymphoma), Cflar (CASP8 and FADD-like apoptosis regulator), and Nkg7 (natural killer cell group 7 sequence)." (PMID 36552094, 2022). "We propose that NKG7 exerts the same function in cytotoxic CD4+ T cells including TFK cells, leading to GZMK-mediated complement activation or GZMB-mediated activation-induced cell death of target – possibly lymphoma – cells." (PMID 41030456, 2025).
osteosarcoma (2 papers, 2023 to 2024). A usually aggressive malignant bone-forming mesenchymal neoplasm, predominantly affecting adolescents and young adults. "Furthermore, the two CD8 + cytotoxic clusters demonstrated upregulation of NKG7, GZMB, GZMH, GZMK, CCL3, CCL4, and CCL5, suggesting that chemotherapy amplified the cytotoxic function of CD8 + T cells, potentially enhancing their antitumor activity within the osteosarcoma tumor microenvironment." (PMID 39033089, 2024).
sarcoidosis (2 papers, 2025). Sarcoidosis is a multisystemic disorder of unknown cause characterized by the formation of immune granulomas in involved organs. "Specifically, when compared with healthy control T cells, there was a modest upregulation of NKG7 and CCL5 in sarcoidosis lesional T cells." (PMID 39989459, 2025). "NKG7- and CCL5-expressing T cells are not a dominant feature in systemic sclerosis or sarcoidosis." (PMID 39989459, 2025).
Stroke (2 papers, 2024 to 2025). Sudden impairment of blood flow to a part of the brain due to occlusion or rupture of an artery to the brain. "Notably, following stroke induction, the population of double-negative T cells (DNTs) (CD3+, CD4-, CD8-, NKG7-) showed significant variation." (PMID 40018035, 2025).
viral infection (2 papers, 2022 to 2025). "It has been reported that genes related to cytotoxicity, such as Granzymes, NKG7, and IL18RAP, are upregulated in CD4+ CTLs in a mouse viral infection model, similar to what we saw in the present study, suggesting that these genes are generally induced in CD4+ CTLs upon viral infections." (PMID 36077655, 2022). "Additionally, the NKG7 gene is highly expressed in natural killer (NK) cells and CD8+ effector memory T cells (CD8 TEM), contributing to cytotoxic responses and aiding these cells in combating viral infections and tumor cells." (PMID 40759922, 2025).
visceral leishmaniasis (2 papers, 2022 to 2024). A severe form of leishmaniasis characterized by irregular bouts of fever, substantial weight loss, swelling of the spleen and liver, and anemia (which may be serious). "In this review, we will discuss recent findings about two of these molecules; the NK cell granule protein Nkg7 and the anti-inflammatory cytokine TGFβ, and describe how they impact CD4+ T cell functions and immune responses during visceral leishmaniasis." (PMID 38881737, 2024).
asthma (1 paper, 2023). "For the NK cell PBMC asthma module, we identified perforin (PRF1) and NK cell granule protein (NKG7) as key drivers that were each also associated with asthma." (PMID 37730635, 2023). "Increased expression of PRF1 in peripheral blood lymphocytes of both allergic and intrinsic asthmatics has been previously reported, and NKG7 was found in a study of publicly available gene expression data to be a marker of severe asthma." (PMID 37730635, 2023). "These causal mediation models revealed that the nasal key drivers of asthma significantly mediate the association between PBMC key drivers in the NK cell module (PRF1 and NKG7) and asthma (FDR = 0.0076 to 0.01)." (PMID 37730635, 2023). "Specifically, we sought to examine causal mediation between PBMC key drivers associated with asthma (PRF1 and NKG7 in the NK cell module; CAPZA2, ATP6AP2, CTSS, and RAB3D from the interleukin module) and nasal key drivers associated with asthma (G3BP1 and INADL from the nasal TCA module)." (PMID 37730635, 2023). "Probabilistic causal network and key driver analyses identified NK cell granule protein (NKG7, fold change = 22.7, FDR = 1.02 × 10−31) and perforin (PRF1, fold change = 14.9, FDR = 1.31 × 10−22) as key drivers predicted to causally regulate PBMC asthma modules." (PMID 37730635, 2023).
bovine tuberculosis (1 paper, 2024). "Other genes found in the present study related to immunity and adaptation in literature were DNAJC17 (heat tolerance in Zebu cattle), GCHFR, MDGA2 (heat stress in cows), FOXF1, NKG7 (bovine tuberculosis response), and SIGLEC10." (PMID 39766784, 2024).
Cachexia (1 paper, 2022). Severe weight loss, wasting of muscle, loss of appetite, and general debility related to a chronic disease. "Indeed, differential gene expression analysis of CD8+ T cells showed significantly higher expression of genes representing activated state in cachexia patients, including GZMH, GZMA, NKG7, and IFNG." (PMID 36376273, 2022).
colon carcinoma (1 paper, 2022). "Unexpectedly, we found that highly CD8+ T cell-immunogenic murine colon carcinoma (MC38-OVA) tumors grew at an equal rate in Nkg7+/+ and Nkg7-/- littermate mice, suggesting NKG7 may not be necessary for effective CD8+ T cell anti-tumor activity." (PMID 35874669, 2022).
cytomegalovirus infection (1 paper, 2021). A herpesvirus infection caused by Cytomegalovirus. "Principal component analysis of the five SLAMF7 and NKG7 splice variants, which expression was influenced by prior CMV infection, revealed two components." (PMID 35087511, 2021). "Moreover, we found that prior CMV infection was associated with a higher relative gene expression of SLAMF7 and NKG7." (PMID 35087511, 2021). "In addition, expression levels of SLAMF7 and NKG7 were affected by prior cytomegalovirus infection in LTx recipients." (PMID 35087511, 2021).
epilepsy (1 paper, 2021). A brain disorder characterized by episodes of abnormally increased neuronal discharge resulting in transient episodes of sensory or motor neurological dysfunction, or psychic dysfunction. "The PPI showed that there are six resistance genes (CD247, CTSW, IL2RB, MATK, NKG7, and PRF1) that may play a central role in the resistance of epilepsy patients." (PMID 34805265, 2021).
heart failure (1 paper, 2025). Inability of the heart to pump blood at an adequate rate to meet tissue metabolic requirements. "The effects of NKG7 and CP expression on heart failure were less known, which required more attentions to illustrate the effects on cardiac remodeling and inflammation resolution." (PMID 40060963, 2025).
IgA nephropathy (1 paper, 2025). "Several studies have demonstrated that the expression of NKG7 was increased in CD8+ T cells in patients with type 1 diabetes mellitus and those with progressive with IgA nephropathy." (PMID 40837024, 2025).
immune thrombocytopenia (1 paper, 2025). "•We analyzed the effect of NKG7 in CD8+ T cells in primary immune thrombocytopenia (ITP)." (PMID 40837024, 2025).
infectious mononucleosis (1 paper, 2022). A condition characterized by an increase in mononuclear white blood cells and swollen lymph nodes, which is usually caused by infection with the Epstein-Barr virus. "In humans, CD4+ CTLs from infectious mononucleosis patients or CMV-infected individuals have been shown to express Tbx21, Granzymes, and NKG7, as we have demonstrated." (PMID 36077655, 2022).
influenza (1 paper, 2019). An acute viral infection of the respiratory tract, occurring in isolated cases, in epidemics, or in pandemics; it is caused by serologically different strains of viruses (influenzaviruses) designated A, B, and C, has a 3-day incubation period, and usually lasts for 3 to 10 days. "The top five genes of each of the two clusters (NK cell activity; NK and T‐cell activity) that were most closely correlated with influenza antibody titers had seven genes (SPON2, AKR1C3, PRF1, FCRL6, GZMA, CSTK, NKG7) which belong to the aging signature genes of IL‐7Rαlow EM CD8+ T cells." (PMID 31044512, 2019).
multiple myeloma (1 paper, 2022). "Identification of a rare cytotoxic NKG7+ plasma cell population in multiple myeloma (MM)." (PMID 36315425, 2022).
myeloma (1 paper, 2022). "(F) Immunofluorescence confirmed the expression of NKG7 in cytoplasm of myeloma cells (CD138 positive) from patients with MM; NKG7 red, CD138 green, bar = 10 μm." (PMID 36315425, 2022). "In another MM single-cell dataset focusing on PC heterogeneity of symptomatic and asymptomatic myeloma (dataset GSE117156), one cluster, C21, exclusively expressing NKG7 corresponded to PC18 in our dataset." (PMID 36315425, 2022).
myxoma (1 paper, 2024). A benign soft tissue neoplasm characterized by the presence of spindle and stellate cells, lobulated growth pattern, and myxoid stroma formation. "Lymphocytes within myxoma tissues exhibit elevated expression of certain genes associated with extracellular matrix adhesion, while their capacity to express cytotoxic molecules such as GNLY, GZMB, and NKG7 is diminished." (PMID 39090109, 2024).
non-small cell lung carcinoma (1 paper, 2025). A group of at least three distinct histological types of lung cancer, including non-small cell squamous cell carcinoma, adenocarcinoma, and large cell carcinoma. "A recent study reported that non-small cell lung cancer showing a complete pathological response to immunotherapy exhibits a stronger immune infiltrate, characterized by higher levels of IFNG, GZMB, NKG7, and M1 macrophages." (PMID 39888994, 2025).
psoriasis (1 paper, 2025). An autoimmune condition characterized by red, well-delineated plaques with silvery scales that are usually on the extensor surfaces and scalp. "Correspondingly, cytotoxic mediators such as PRF1, GZMA, SRGN, and NKG7 were upregulated, paralleling signatures seen in αβ T cells in psoriasis." (PMID 41181116, 2025).